HIF1A (hypoxia inducible factor 1 subunit alpha)
Diseases named in the same sentence as HIF1A in open-access papers (continued):
Sharing a sentence is not in itself a finding about the gene and the disease.
cancer (continued). "Exposure of OSCC cells to hypoxia was further shown to induce autophagy by activating the signaling pathway of Hypoxia-inducible factor 1-alpha (HIF-1α)/Bcl-2 interacting protein 3 (BNIP3)/Beclin-1 and inducing HMGB1 secretion, thus acting as a survival mechanism for the cancer cells." (PMID 37511951, 2023). "The downregulated HIF1α and VEGF strengthened the inhibitory effect of CA4P on angiogenesis, creating a closed‐loop reinforcement for the obstruction of extracellular energy supply and cancer cell migration." (PMID 37156756, 2023). "It has been reported that lung mesenchymal cells in the pre-metastatic niche induce an increase of lipids storage in neutrophils through the PGE2- HIF1α–HILPDA axis, and those neutrophils promote the growth of disseminated cancer cells by feeding them lipids during the early stage of colonization." (PMID 37174093, 2023). "Finally, the molecular docking and core ingredients analysis showed that quercetin was the core ingredient of JQH and bound well with several inflammation-cancer targets, including AKT1, EGFR, HIF1A, and IL6A." (PMID 37964307, 2023). "We found significant higher levels of HIF-1α (125.8 pg/ml, SEM = 48.66 pg/ml) in EVs from COPD subjects who subsequently developed cancer (i.e. before CT scan detection) than COPD subjects who remained cancer free for at least three years (12.34 pg/ml, SEM = 2.835 pg/ml) (*p = 0.04)." (PMID 37838700, 2023). "Hypoxia promotes the expression of HIF-1α and ALKBH5; ALKBH5 regulates the expression of ITGB1 in an m6A-YTHDF2-dependent manner, triggers the phosphorylation of FAK and Src, and promotes EOC cancer lymphangiogenesis and metastasis." (PMID 36632222, 2023). "Additionally, metformin promotes the cancer-killing capacity of CD8+ T-cells by modulating glycolysis and downregulates immune checkpoint expression and glycolytic flux through HIF-1α inhibition." (PMID 36768924, 2023). "Future experiments should aim to elucidate the connection between TIGIT and other immune checkpoints, particularly those involved in the immune response against cancers which do not express PD-L1, as well as the interplay with HIF-1α and the A2A receptor." (PMID 36874131, 2023). "TLR4 signaling has been shown to lead to the accumulation of HIF-1α, a key transcriptional regulator of CAMs, and the IRE1α-XBP1 signaling axis enhances HIF-1α transcriptional activity without affecting HIF-1α protein levels in cancer cells." (PMID 36475773, 2023). "In 3D tumoroid structures with an average diameter of 500 μm or more, the existence of hypoxia in the innermost zone led to the promotion of angiogenesis factors HIF-1α, P-glycoprotein, and VEGF, leading to cancer cell resistance and recapitulating in vivo conditions." (PMID 37337165, 2023). "We aimed to investigate potential new drug therapy options for targeting hypoxic cancer cells within HCC tumors, specifically through combining HIF-1α inhibition with palmitic acid (PA) + L-carnitine (LC) treatment to effectively induce apoptosis in hypoxic HCC cells." (PMID 38066600, 2023). "Therefore, HIF-1α and PKM2 are recognized as major drivers of cancer metabolism participating in a positive feedback loop that enhances the Warburg effect and feeds the glycolysis branch pathways." (PMID 37305566, 2023). "Mechanistically, PGAM1 overexpression in KIRC may be attributed to metabolic abnormalities or the high energy requirements of metastatic cancer cells, as PGAM1 and HIF1A exhibit direct regulation." (PMID 37847178, 2023). "Cellular senescence is the last but not the least limitation for the action of HIF-1α inhibitors in surpassing cancer chemoresistance." (PMID 36846589, 2023). "In fact, metformin modifies the energetic activity of cancer cells by blocking complex 1 of the electron transport chain, restricting the activity of the protumor isoform HK2, and downregulating the expression of HIF-1α and mTOR." (PMID 38292487, 2023).
cancer (continued). "HIF-2α was found to be present within the CSC population, while HIF-1α was present in both stem and non-stem cancer populations." (PMID 37614497, 2023). "hypoxia inducible factor-1α (HIF-1α) and pyruvate kinase M2 (PKM2) are 2 key metabolic regulatory proteins, they could engage in a positive feedback loop and drive cancer growth by enhancing glycolysis." (PMID 36897686, 2023). "Due to this, a strategy where the HIF-1α stabilization-mediated increase of OATP expression is used to enhance the drug accumulation to cancer cells likely would not lead to a more efficient therapy response." (PMID 36839686, 2023). "It is reported that the proximal promoter of PD-L1 is directly bound to the hypoxia response element in HIF-1a, in favor of speculating that HIF-1α/PD-L1 may be a new target for cancer immunity." (PMID 37608888, 2023). "HIF-1α mediates hypoxic and non-hypoxic signaling pathways and plays a crucial role in cancer progression." (PMID 37333486, 2023). "AXL is a receptor tyrosine kinase expressed in different cancer cell types, and the gene expression is regulated by HIF1α and HIF2α in hypoxic cancer cells lacking VHL protein." (PMID 37190141, 2023). "Since both HIF-1α and HIF-2α have been identified as PD-L1 transcription factors in cancer cells in response to hypoxia, we then reasoned whether ATXN3 enhances tumoral PD-L1 transcription through stabilizing HIF family transcription factors." (PMID 38038129, 2023). "On the contrary, culturing the cancer cell lines with medium from untreated PBMC cultures from a healthy donor resulted in PD-L1 up-regulation in all cell lines, including the ones with silenced HIF1α gene." (PMID 37067635, 2023). "Together, these data suggest that SP1, HIF1A, and MYC have crucial roles in cancer development, and that interfering with their activity could negatively impact cancer development and progressions." (PMID 37998757, 2023). "Additionally, other autoantibodies targeting SOX2, HIF1-α, NY-ESO-1/CTAG1B, MUC1, Her2, GAL1, and GAL3 have been frequently identified in cancer patients." (PMID 37627091, 2023). "In our study, we found that silencing NFATc2 in the EtOH-exposed OSCC cells resulted in a decrease in multiple genes involved in glycolysis and cancer stemness, including HIF1α, TP1, ENO1, PKM2, ALDH1A, Bmi1, and Oct4 (data not shown)." (PMID 36077186, 2022). "In different types of tumors, cancer cells produce factors involved in the myelopoiesis (VEGF, GM-CSF, IL-1β, IL-6, HIF-1α, TGF-β, COX-2), as well as in the recruitment (CCL2, CCL3) and activation (TNF-α, IL-10, IL-1β, IL-6, INF-γ, COX-2, HIF-1α) of MDSCs." (PMID 35160177, 2022). "As the involvement of HIF-1α in the etiology of hepatic fibrinogenesis is well reported because of its pathological activity, targeting HIF will be a promising choice to impede the development of fibrosis and cancer." (PMID 36523459, 2022). "Most current studies focused on the relationship between cancer and HIF-1α in the context of hypoxia have limited insight because about 50% of advanced solid tumors lack hypoxic zones, and as a result, they remain able to activate HIF-1α." (PMID 36003773, 2022). "HIF-1α is a transcription factor that controls glycolytic gene expression, and SIRT3 mediates metabolism reprogramming by destabilizing HIF-1α to affect the progression of cancer." (PMID 35832551, 2022). "In addition, Ole (0.04% of diet) was reported to reduce HIF-1α, and adipogenesis in B16F10 melanoma cells in mice fed a high-fat diet led in cancer progression prevention." (PMID 36013319, 2022). "Our results underline that SIRT3 effects can be highly cancer cell context specific, a point that is nicely illustrated by the lack of effect of SIRT3 depletion on HIF1α functions in DLBCL cells." (PMID 35019856, 2022). "HIF-1α is a subunit of the HIF-1 transcription factor, a master regulator of hypoxia, and an oncogenic protein promoting malignant phenotypes of breast cancer and other human cancers." (PMID 35853854, 2022).
cancer (continued). "A short treatment with two specific STAT3 inhibitors significantly reduced HIF-1α in BM macrophages after a 2 hr incubation with apoptotic cancer cells; however, HIF-1α stabilization was not completely abrogated." (PMID 36496973, 2022). "HIF-1α promotes metastasis in cancer tissues via SMAD and non-SMAD signaling pathways by up-regulating TGF-β expression." (PMID 36014432, 2022). "Notably, several cancer‐related pathways that contain the lactate dehydrogenase A (LDHA) gene were enriched, including the hypoxia‐inducible factor (HIF) pathway, the HIF‐1α transcription factor network, and the lactate fermentation pathway." (PMID 36307872, 2022). "HIF-1α transcriptionally upregulates the expression of CD47, which helps to escape the phagocytosis of macrophages and maintain the stem phenotype of breast CSCs (cancer stem cells)." (PMID 36139678, 2022). "However, it is quite clear that the activation of HIF-1α and HIF-2α has a clear link with cancer development." (PMID 36523459, 2022). "The regulation of USP2-AS1 by MYC and HIF1α suggests that it might take part in the crosstalk between the MYC and HIF1α signaling pathways during cancer initiation and progression." (PMID 36359803, 2022). "Indeed, the stabilization of HIF-1α has been reported to induce GLUT1 expression in a HIF-1α -dependent manner, increasing cellular glucose uptake and supporting aerobic glycolysis in cancer cells." (PMID 36408139, 2022). "Therefore, we systematically and comprehensively analyzed HIF1α using GEPIA, HPA, GeneMANIA, STRING, SMPDB, cBioPortal, UALCAN, and TISDB databases and also 33 cancer and normal tissues in TCGA downloaded from the Genome Data Commons (GDC) data portal." (PMID 35860430, 2022). "Thus, hypoxia and HIF1α activate Wnt/β-catenin signaling via BCL9, resulting in cancer cell proliferation and metastasis." (PMID 35027586, 2022). "Taken together, these results suggest that MAP2K2, LUM, RPS6, PDCD4, TWIST1, and HIF1A may play important roles in DMD pathophysiology by regulating the MAPK pathway and proteoglycans in cancer." (PMID 36619896, 2022). "Among them, the expressions of T cell CD4+ central memory, T cell CD4+ Th1, and HIF1α have the strongest negative correlation in various cancers." (PMID 35860430, 2022). "It was also reported that HIF-1α could promote metastasis and EMT through increasing ROS expression level in cancer cells." (PMID 36071871, 2022). "Thus, the relevance of HIF-1α and the signaling molecules involved in PC formation and NPHP3 expression to regulate cancer cell viability are further clarified." (PMID 36498831, 2022). "In addition, all of these cell types, as well as cancer cells, secrete VEGF in response to HIF-1α (hypoxia-inducible factor-1 alpha), which helps to recruit blood vessels and to stimulate further angiogenesis in tumors." (PMID 35163805, 2022). "Cancer cells were also shown to adapt their metabolism under desmoplastic conditions, independent of oxygen levels and HIF1A." (PMID 36612058, 2022). "The supplemented O2 by PMCs inhibited HIF-1α production and NF-κB activation in cancer cells and dramatically prevented cancer cell duplication in a nontoxic manner." (PMID 35918337, 2022). "Thus, hypoxia and activity of IGF-I are two parallel paths for the induction of HIF-1 in cancer, and the expression of HIF-1α and vascular endothelial growth factor (VEGF) in CRC tissues was proposed to serve as a biomarker of cancer progression." (PMID 36013453, 2022). "Thus, deacetylation of HIF-1α at K532 increases the stability of HIF-1α, leading to migration and invasion of cancer cells." (PMID 35869366, 2022). "HIF-1α regulates the expression of various genes related to cancer cells proliferation and apoptosis, angiogenesis, metastasis, cancer metabolism, CSC maintenance, and chemoresistance to various cancers." (PMID 35885540, 2022).
cancer (continued). "Molecular mechanisms underlying the acquisition of chemoresistance coordinated by Notch1 signaling are thought to include induction of epithelial-mesenchymal transition (EMT), formation of cancer stem cells (CSCs), and increased expression of MDR1, MRP1, BCRP, and HIF-1α." (PMID 36297616, 2022). "HIF-1α can regulate CSC properties that are responsible for drug resistance and cancer recurrence." (PMID 36014432, 2022). "HIF-1α is another anti-cancer target that was found to be inhibited by carboranes, where they prevented hypoxia-induced HIF-1α accumulation without affecting the expression level of HIF-1α mRNA." (PMID 35337063, 2022). "Pretreatment of cancer cells with actinomycin D, a transcription inhibitor, almost abolished EGF-enhanced HIF-1α expression in GSCs, LN229, and U251 cells, suggesting that transcriptional regulation of HIF-1α is essentially involved in response to EGFR activation." (PMID 36435833, 2022). "Cancer cells maintain aerobic glycolysis and HIF-1α stability despite the absence of hypoxia by the AKT/mTOR pathway or AMPK signaling pathway." (PMID 36059650, 2022). "While Resveratrol did not affect cancer cell proliferation either in the scaffold or in monolayer cultures, it markedly decreased HIF‐1α expression in both cell lines." (PMID 34109737, 2022). "Repressing HIF-1α could effectively restore proliferation and invasiveness in MCF-7 cancer cells previously treated with the antidiabetic drug." (PMID 36139678, 2022). "HIF-1α and HIF-2α are overexpressed in many types of cancers." (PMID 36618350, 2022). "Most remarkable, the expression of T cell CD4+ central memory, T cell CD4+ Th1, and HIF1α has the strongest negative correlation in various cancers." (PMID 35860430, 2022). "The circ0000977/miR-153/HIF1A/ADAM10 axis may be used as an immune sensitizer to treat and/or prevent cancer." (PMID 36238299, 2022). "Therefore, HIF-1α not only has a prominent role in EMT, it can also regulate metastasis to accelerate the virulence of different cancers." (PMID 36014432, 2022). "The activation of the PI3K/Akt pathway, which upregulates HIF-1α through multiple pathways, drives the expression of VEGF to enable the migration of endothelial cells to form a neovasculature network, so as to promote the growth and metastasis of cancer cells." (PMID 35321703, 2022). "There is also evidence that a nonmodified by ERKs mitochondrial HIF-1α form protects cancer cells from apoptosis under hypoxia." (PMID 35406562, 2022). "Moreover, eight axes (e.g., OIP5-AS1/miR-124-5p/IDH2) are involved in key pathways, such as Wnt/b-catenin, E2F1, TGF-β, SMAD, ERK/MAPK, HIF-1α, Notch, PI3K/Akt signaling, and cancer cell stemness." (PMID 36362406, 2022). "In particular, c-MYC and HIF-1α promote the expression of glycolytic enzymes hexokinase 2 (HK2), phosphofructokinase 1 (PFK1), triosephosphate isomerase 1 (TPI1), lactate dehydrogenase A (LDHA) in cancer." (PMID 36313705, 2022). "The results indicate that the compression-enhanced cancer cell invasion was largely unaffected no matter the cells were treated or not with HIF-1α inhibitor." (PMID 34979904, 2022). "Therefore, it indicates that miR-153 regulates HIF1α/VEGF axis in angiogenesis, proposing usage as an anti-angiogenesis therapy in cancer." (PMID 36158686, 2022). "Given the cancer specificity of PFKFB4, such compounds could open up a whole new avenue for inhibiting HIF-1α in a cancer specific manner." (PMID 36115843, 2022). "Second, are there any cancer-related targets other than CKAP2 co-regulated by DLEU1 and HIF-1α?" (PMID 35853854, 2022).
cancer (continued). "Considering it is estimated that over 40% of cancers overexpress MYC, it may be beneficial to target HIF-1α and MYC using overlapping pathways and direct or indirect HIF-2α targets." (PMID 35267567, 2022). "In addition, the HIF1A protein is overexpressed in hypoxic tumors; the cancer stem cell marker CD24 is also overexpressed in many tumors, confirming the correlation whereby HIF1A leads to CD24 overexpression in hypoxic tumors." (PMID 35659268, 2022). "HIF-1α inhibitors are warranted for cancer treatment regimens; however, no specific HIF-1α inhibitor has gained clinical approval to date due to complex upstream regulation and intertwined mechanisms." (PMID 36319626, 2022). "Furthermore, the co-occurrence of low RBC numbers in the lungs with increased HIF1α levels in 40-week-old compared to 20-week-old BALB/c mice suggests impaired pulmonary perfusion that might also contribute to a hypoxic micro-environment favouring cancer progression." (PMID 36504711, 2022). "It has been shown that downregulation of IDH3α in CAFs switches the cancer cell metabolism to aerobic glycolysis by stabilizing HIF-1α, but not HIF-2/3α, in an α-ketoglutarate-dependent manner." (PMID 35884382, 2022). "Similarly, we found that drug resistant CRC cells displayed EMT features and enhanced HIF1α expression, which facilitating EMT conversion in various cancer cells." (PMID 35355718, 2022). "This metabolic phenomenon, known as aerobic glycolysis or the Warburg effect, can occur even under nonhypoxic conditions, indicating that HIF-1α is a central regulator of cancer metabolism." (PMID 36139067, 2022). "HIF-1α and HIF-2α factors activate the expression of MMPs (MMP1, −2, −9, −14) that participate in the degradation of extracellular matrix components and degrade the basement membrane, which results in easy migration and spread of cancer cells." (PMID 36139678, 2022). "In addition, LSD1 is highly expressed in cancers, potently stabilises HIF1α and enhances the transcriptional activity of downstream target genes, such as VEGF, which can induce cancer angiogenesis." (PMID 36059955, 2022). "In addition, PKM2 can interact with transcription factors, such as HIF-1α, β-catenin/c-Myc, NF-κB and STAT3 to promote target genes transcription and enhance cancer cells growth and angiogenesis." (PMID 36471428, 2022). "HIF-1α is the regulatory subunit in the formation of active HIF1, it is expressed under hypoxic conditions, and its expression is related to the Warburg effect in cancer." (PMID 36678382, 2022). "Moreover, the levels of HIF-1α, Cyclin D1, c-Myc, and OCT4 were elevated in TRIB2-overexpressed cancer cells, which further promote cancer cell proliferation." (PMID 35790734, 2022). "If targeting intratumoral hypoxia/HIF-1α using NBO2 water without side effects is made possible, treatment of high-risk cancer patients who cannot tolerate surgery or systemic chemotherapy would be feasible." (PMID 35743281, 2022). "Thus, we investigated 2-ME as a potent anti-cancer and hypoxia-inducible factor 1 alpha (HIF-1α) inhibitor drug that prevents RISI by targeting HIF-1α." (PMID 35456989, 2022). "In human hepatocellular carcinoma HepG2 cell line, HIF-1α increased the level of COX-2 protein and induced EMT process to cope with hypoxic environment, leading to increased invasiveness and metastasis of the cancer cells." (PMID 35897065, 2022). "In addition, the inhibition of the von Hippel–Lindau (VHL) tumor suppressor, the primary negative regulator of HIF1a, results in CD8+ T cells showing an enhanced ability to control cancer growth." (PMID 35203357, 2022). "Moreover, eight axes are involved in key pathways: Wnt/b-catenin, E2F1, TGF-β, SMAD, ERK/MAPK, HIF-1α, Notch, PI3K/Akt signaling, and cancer cell stemness." (PMID 36362406, 2022).